CDKN2A (cyclin dependent kinase inhibitor 2A)
Diseases named in the same sentence as CDKN2A in open-access papers (continued):
Sharing a sentence is not in itself a finding about the gene and the disease.
pulmonary fibrosis (20 papers, 2015 to 2025). Chronic progressive interstitial lung disorder characterized by the replacement of the lung tissue by connective tissue, leading to progressive dyspnea, respiratory failure, or right heart failure. "The inhibition of CDKN2A in M2 macrophages using palbociclib successfully reduced the extent of pulmonary fibrosis in a BLM‐induced lung injury mouse model." (PMID 41409095, 2025). "CDKN2A was significantly upregulated within lung samples in pulmonary fibrosis individuals, and this upregulation increased with disease severity." (PMID 35682685, 2022). "CAV1, NOS2, GDF15, and CDKN2A were demonstrated to be influencing the development of pulmonary fibrosis by regulating ferroptosis." (PMID 35069688, 2021). "Furthermore, these cells are the primary source of integrin αvβ6 and exhibit high expression of MMP7 and CDKN2A, which are associated with ECM remodeling and epithelial cell senescence, respectively, during the process of pulmonary fibrosis." (PMID 41409095, 2025). "Fibrosis-related genes include Col1a1, Acta2, Fn1, and Tgfb1 gene, and senescence-related genes composed of Cdkn2a, Tnf, Serpine1, Ccl2, Mmp10, and Mmp12 gene, all of which reflected the intensity of lung fibrosis and senescence events in lung tissue and pulmonary fibroblasts." (PMID 35662697, 2022). "CAV1, NOS2, GDF15, CDKN2A may influence the development of pulmonary fibrosis by regulating ferroptosis." (PMID 35069688, 2021). "In conclusion, this study underscores the pivotal role of cellular senescence in the pathogenesis of idiopathic pulmonary fibrosis (IPF) and identifies four key CS-DEGs (CDKN2A, VEGFA, SOX2, and FOXO3) as potential biomarkers for diagnosis and targets for therapy." (PMID 40557159, 2025).
viral infection (20 papers, 2010 to 2024). "However, the change in the expression of p16 (a protein encoded by CDKN2A) could be not only outcome virus infection but also DNA damage and gene mutation." (PMID 36551770, 2022). "Using whole-genome next-generation DNA sequencing analysis, this deletion was shown to include the CDKN2A/B tumor-suppressor-gene locus and the type I interferon gene cluster, which may contribute to the tumorigenic potential and high susceptibility of VERO cells to viral infection, respectively." (PMID 36279283, 2022).
invasive carcinoma (19 papers, 2004 to 2026). A carcinoma that is not confined to the epithelium, and has spread to the surrounding stroma. "Likewise, p16 protein expression is often used as a surrogate marker for high‐risk HPV, and the correlation between p16 and CDKN2A as well as the correlation between CDKN2A and high‐grade dysplasia/invasive carcinoma in HPV‐associated cases was also high." (PMID 41129372, 2026). "Moreover, progression to invasive carcinoma could be linked to 9p21.3 loss, encompassing the type I interferon gene cluster and CDKN2A, pointing towards a crucial role in therapy resistance and carcinogenesis." (PMID 38706595, 2024).
liposarcoma (19 papers, 2017 to 2026). A usually painless malignant tumor that arises from adipose tissue. "There have been several studies, including a phase 2 clinical trial in liposarcoma and dedifferentiated liposarcoma, investigating the efficacy of cyclin-dependent kinase 4/6 inhibitors such as palbociclib in the setting of CDKN2A loss." (PMID 35582536, 2022). "Leiomyosarcomas and liposarcomas were found to infrequently have CDKN2A aberrations at a ≤ 10% rate." (PMID 31528332, 2019). "The expression of two inhibitors of Cdk4, Cdkn2a and Cdkn2b, was significantly increased, as a late event, present only in DAKO liposarcomas." (PMID 28459858, 2017). "CDKN2A/B), amplifications (e.g. JUN in liposarcoma), fusion partners (e.g. PAX3/7::FOXO1 in rhabdomyosarcoma), breakpoint positions in fusions (e.g. NAB2::STAT6 in SFT) and the extent of segmental (i.e. sub-chromosomal arm) copy number changes (e.g. synovial sarcoma)." (PMID 38997407, 2024).
lung squamous cell carcinoma (19 papers, 2013 to 2025). "Studies have shown that the SOX2 in tracheobronchial cells overexpressed with CDKN2A and PTEN deletion combination results in lung squamous cell carcinoma production." (PMID 36056339, 2022).
lymph node metastasis (19 papers, 2006 to 2024). "Hypermethylation of other genes were associated with lymph node metastasis, such as CDKN2A/p16 and CDKN2A/p1445, DFNA546,47, HLTF23, and ESR1." (PMID 34827720, 2021). "Furthermore, the best diagnostic model for lymph node metastasis, which included CDKN2A, PLAU and other clinicopathologic parameters was analyzed." (PMID 33968767, 2021). "Hence, in agreement with previous studies, two patients with adjacent organs invasion (15.4%), two and four patients occurred lymph node metastasis (15.4%) and intrahepatic metastasis (30.7%), respectively, in our study, maybe partially owing to the CDKN2A mutation." (PMID 37428205, 2023). "The prediction model including CDKN2A, PLAU, T stage and pathological grade can be used as the best diagnostic model for lymph node metastasis in OSCC." (PMID 33968767, 2021). "High expression of CDKN2A and PLAU was associated with lymph node metastasis in OSCC." (PMID 33968767, 2021). "The model with the combination of CDKN2A, PLAU, T stage and pathological grade was the best in predicting lymph node metastasis (AUC = 0.807, 95% CI: 0.713-0.881, P=0.0001)." (PMID 33968767, 2021). "TSGs such as CDKN2A and FAM134B were found to be hypermethylated in CRC patients with lymph node metastasis and in patients with LVI, highlighting the potential involvement of multiple hypermethylated TSGs in the metastatic cascade and the invasive traits of CRC." (PMID 38255946, 2024). "constructed a prediction model for nodal metastasis based on molecular panel and clinicopathological factors in 112 cN0 OSCC patients, the model with the combination of CDKN2A, PLAU, T stage and pathological grade was the best in predicting lymph node metastasis (AUC = 0.807)." (PMID 37016465, 2023).
nasopharyngeal carcinoma (18 papers, 2010 to 2025). A carcinoma arising from the nasopharyngeal epithelium. "CDKN2A gene which regulates the arrest of cell cycle at the G2 phase is hypo‐methylated in radio‐resistant nasopharyngeal carcinoma cells." (PMID 29952116, 2018). "Similar CDKN2A methylation patterns have been observed in gastric and nasopharyngeal carcinoma." (PMID 27893424, 2017). "For the first time, our study highlights that all EBVaGC cases exhibit intact CDKN2A, a stark contrast to nasopharyngeal cancer (NPC), where over 30% of cases show CDKN2A deletion, particularly in EBV‐positive instances." (PMID 39844467, 2025). "MiR-663 was also shown to increase the proliferation of nasopharyngeal carcinoma NPC C666-1 cells by directly targeting the cell cycle negative regulator CDKN2A." (PMID 29987196, 2018).
nevus (18 papers, 2003 to 2025). Nevus (or naevus, plural nevi or naevi, from nævus, Latin for "birthmark") is the medical term for sharply circumscribed[1] and chronic lesions of the skin or mucosa. "Genetic predisposition, including pathogenic variants in CDKN2A, was strongly associated with an increased risk, along with a high total nevus count, particularly atypical nevi." (PMID 39941357, 2025). "Genome-wide association studies have indeed reported several genes involved in nevus count, including CDKN2A and MTAP, both located at the 9p21 locus, and PLA2G6, located at 22q13." (PMID 24915306, 2014). "Falchi and colleagues hypothesized that the gene methythoiadenosine phosphorylase (MTAP) or the adjacent CDKN2A gene are involved in the nevus formation." (PMID 26938746, 2016). "We used linkage and association analysis in adolescent twins from the UK to examine the hypothesis that the region containing the CDKN2A gene also contains a quantitative trait locus influencing normal nevus development." (PMID 12799637, 2003). "Therefore, CDKN2A germline mutations appear to be more correlated with the atypical, rather than with the common, nevus count." (PMID 34356093, 2021). "Despite this, p16INK4A expression is neither ubiquitous across melanocytic nevi, nor uniform within the cells of a single nevus, and neither knockdown of the 16INK4A transcript nor ablation of the CDKN2A locus prevents the onset or rescues BRAFV600E-induced proliferation arrest." (PMID 34812139, 2021).
pleural mesothelioma (18 papers, 2015 to 2026). A neoplasm that arises from the mesothelial cells of the pleura. "CDKN2A deletion is a common alteration in pleural mesothelioma (PM) and frequently associated with co-deletion of MTAP." (PMID 37894345, 2023). "Loss of the CDKN2A gene and its protein p16 is a common event in pleural mesothelioma, which is frequently investigated to confirm the diagnosis." (PMID 37894345, 2023). "The most altered gene in pleural mesothelioma is CDKN2A, which encodes for inhibitors of the cyclin-dependent kinases 4 and 6 (CDK4/6) involved in cell-cycle regulation." (PMID 36138075, 2022). "In CDKN2A-mutated malignant pleural mesothelioma cell lines and in a mouse model, the inhibition of CDK4/CDK6 was shown to suppress cell viability and tumour growth." (PMID 32526924, 2020). "We previously demonstrated that in BAP1-proficient pleural mesothelioma cells, CDKN2A is critical for mediating the response to selective EZH2 inhibition and highlighted a complex interplay between epigenetic regulation and the tumor immune microenvironment." (PMID 41226368, 2025). "Along with the 2021 WHO Classification of Thoracic Tumours, recent literature on the topic states that MTAP immunohistochemistry is a highly specific and sensitive surrogate of FISH to detect CDKN2A HD in pleural mesothelioma." (PMID 40566743, 2025). "MTAP immunohistochemistry (IHC) has been proposed as a cheaper and more reproducible surrogate for CDKN2A homozygous deletion (HD) detected by FISH in pleural mesothelioma." (PMID 40566743, 2025). "BRCA-1-associated protein 1 (BAP1), Cyclin-Dependent Kinase inhibitor 2A (CDKN2A), and Neurofibromatosis type 2 (NF2) are the genes most frequently altered in pleural mesothelioma." (PMID 37835398, 2023). "In pleural mesothelioma, Group 1 had alterations in CDKN2A/B and BAP1, Group 2 in CDKN2A/B only, Group 3 in BAP1 only and Group 4 in neither BAP1 nor CDKN2A/B." (PMID 36138075, 2022). "As recommended for inclusion in pathological reports of pleural mesotheliomas, we also analyzed p16/CDKN2A deletion and PD-L1 status." (PMID 34294087, 2021). "Somatic mutations in CDKN2A, NF2, BAP1 were also reported in cases of malignant peritoneal mesothelioma, with CDKN2A less frequent as compared to pleural mesothelioma." (PMID 34249695, 2021). "In human cell lines, the expression of Cdkn2a was also considerably decreased in pleural mesothelioma (MPM) relative to normal mesothelial cells (MC) (right)." (PMID 27129173, 2016). "CDKN2A loss is observed in MPM; however, it is less prevalent than in pleural mesothelioma cases." (PMID 39407894, 2024). "In pleural mesothelioma, BAP1, CDKN2A, and NF are the most often mutated genes." (PMID 39407894, 2024). "Loss of CDKN2A is present in MPM, however, less frequently than pleural mesothelioma cases." (PMID 37835398, 2023). "Copy number loss of BAP1, CDKN2A/B, LAST1/2, and NF2 is frequently found in pleural mesothelioma." (PMID 32545767, 2020). "Specifically, we confirmed that the profiles corresponded to expected pleural mesothelioma-specific alterations, including changes in the BAP1 and MTAP/CDKN2A gene regions." (PMID 39920655, 2025). "Cytological diagnosis of pleural mesothelioma (PM) is controversial, even using ancillary markers (BAP1, MTAP and CDKN2A)." (PMID 38067238, 2023). "The five most frequently altered genes in pleural mesothelioma were CDKN2A (48.2%), BAP1 (45.0%), CDKN2B (42.2%), NF2 (32.8%) and MTAP (32.3%), in peritoneal mesothelioma BAP1 (47.9%), NF2 (26.5%), CDKN2A (25.9%), CDKN2B (19.5%), PBRM1 (15.8%)." (PMID 36138075, 2022).
thymoma (18 papers, 2010 to 2026). A neoplasm arising from the epithelial cells of the thymus. "Specifically, CDKN2A promoter methylation has been observed in thymomas and thymic carcinomas, presumably leading to the inactivation of the p16/RB axis, while higher levels of MTHFR methylation were observed in MG-associated TETs." (PMID 36836670, 2023). "Only in one of 17 (6 %) B3 thymomas a mixed heterozygous/homozygous CDKN2A gene deletion was detected." (PMID 27844328, 2017). "Conversely, only one Type B3 thymoma displayed CDKN2A gene loss, and none of the Type A thymomas showed any deletion." (PMID 38338833, 2024). "In thymic carcinomas, but not in type A and B3 thymomas, a lack of p16INK4A expression was largely associated with CDKN2A mutation or gene deletion (data not shown)." (PMID 27844328, 2017). "Interestingly, promoter methylation of the CDKN2A gene was reported in up to 11% of thymomas and 25% of thymic carcinoma, while aberrant MGMT methylation and loss of its protein expression was more frequent in thymic carcinoma than in thymoma." (PMID 27999265, 2016). "Although HPV could not be related to thymomagenesis increased transcript expression of p16 (cyclin-dependent kinase inhibitor 2A) was reported in human thymomas." (PMID 26537237, 2015). "To further address this issue, we investigated MLH1, MGMT, CDKN2A, and RASSF1A methylation levels in blood samples and surgically resected thymomas from 69 patients with TAMG and in the adjacent normal thymus available from 44 of them." (PMID 33192293, 2020). "Previous studies in Asian samples have shown that MLH1, MGMT, CDKN2A, and RASSF1A genes are hypomethylated in thymomas as compared with thymic carcinomas or neuroendocrine tumors." (PMID 33192293, 2020). "The methylation levels of the DNA repair and tumor suppressor genes MLH1, MGMT, CDKN2A, and RASSF1A have frequently been investigated in thymic epithelial tumors (TETs), including thymomas." (PMID 33192293, 2020). "A trend for the absence of co-occurrence with GTF2I was observed also for CDKN2A, BAP1, CYLD, and KIT mutations, which are genes frequently mutated in B3 thymomas and thymic carcinomas." (PMID 37671056, 2023). "While we did not perform CDKN2A FISH in B3 thymomas, none of the B3 thymomas in our study showed loss of mTAP expression, although the number of cases was relatively small." (PMID 35565429, 2022). "In type A thymomas that lacked CDKN2A deletions and type B3 thymomas that rarely (7 %) exhibited CDKN2A deletion a different mechanism must predominate." (PMID 27844328, 2017). "CDKN2A promoter methylation is a known alternative mechanism of p16I INK4A silencing and may dominate in type A and B3 thymomas." (PMID 27844328, 2017).
thymoma (continued). "This was not the case in any TET that we studied functionally, since CDKN2A transcription always increased during thymoma epithelial cell culture." (PMID 29163772, 2017). "In summary, the present study reveals that the promoter methylation levels of MLH1, MGMT, CDKN2A, and RASSF1A genes are not increased in thymomas with respect to the healthy tissues of patients with MG and do not correlate with histological or pathological features." (PMID 33192293, 2020).